CD4 (CD4 molecule)
Diseases named in the same sentence as CD4 in open-access papers (continued):
Sharing a sentence is not in itself a finding about the gene and the disease.
infection (continued). "This highlights an advantage of using this T-cell line compared with using primary CD4+ T cells, which in principle would be more relevant but would require at least 2 × 109 cells and extraordinary viral inocula to achieve a high-multiplicity and synchronized infection." (PMID 35017099, 2022). "In contrast at very early time points during infection, treatment with IFNβ could elevate those cytotoxic effector functions for CD4+ T cells and NK cells especially at the vaginal tract, thereby negatively correlating with the superior reduction of local viral loads in IFNβ-treated mice." (PMID 36325470, 2022). "However, the nature of the infection greatly impacts the evolution of CD4+ T cell functions." (PMID 35829695, 2022). "Moreover, we identified a significant increase in CD4+ CD134 (OX40) in MABS infection (p<0.0001)." (PMID 36439147, 2022). "Thus, in early infection, activating FcR signaling that enhance CD4 T cells are protective." (PMID 35371092, 2022). "A simple score based on clinical symptoms of acute retroviral syndrome during the previous year, CD4+ T cell count, and viral load at admission was tested to assess the predictive power, using receiver operating characteristic (ROC) curves, to identify recent cases of infection." (PMID 35544888, 2022). "However, many of the TH17 cells are no more susceptible to infection in the gut than other CD4+ subsets, suggesting that HIV infection is not the direct cause of TH17 depletion (12, –, 14)." (PMID 35311549, 2022). "Additionally, there are claims for a CD4-independent astrocyte infection pathway via cell-to-cell transfer from infected T cells to astrocytes, where actively budding virus Env protein binds to CXCR4 and facilitates fusion of the immature viral membrane and astrocyte membrane." (PMID 35975998, 2022). "Analysis of the quality of the immune response of the two older donors with HCMV DNA detectable in their saliva also supports this hypothesis, in that these two donors have decreased control of viral spread by their PBMC and CD4+ T cells at the early phase of infection." (PMID 36591233, 2022). "Indeed, both naturally occurring CD4+ Foxp3+ Tregs as well as different myeloid cell subsets, including Ly6C- patrolling monocytes and alternatively activated macrophages, were shown to constitute sources of IL-10 during the early stages of infection." (PMID 35464430, 2022). "Interestingly, IFN-γ production by CD4+ T lymphocytes in the lungs was higher following secondary challenge compared to primary infection with the homologous strain for all examined Brucella spp., although this change was only significant for B. canis and B. melitensis." (PMID 36032120, 2022). "In the absence of infection, age causes dramatic shifts in CD4 subset activity during homeostasis." (PMID 36119079, 2022). "However, compared with other infectious diseases, the accumulation of Mtb-specific CD4+ T cell response in the lungs is delayed in Mtb-infected mouse models from two weeks post-infection, which is related to the obstruction of Ag presentation by Ag-presenting cells (APCs) such as DCs." (PMID 35967869, 2022). "Previous studies have shown that poorly neutralizing antibodies, a Th2-biased immune response and distinct CD4+ T-cell subsets correlate with VED upon RSV infection and that high neutralizing antibody levels correlate with the prevention of disease severity and a lower risk of infection." (PMID 36578490, 2022). "Indeed, fewer CD4+ memory T-cells or long-lived antibody-producing B-cells are generated after vaccination compared to natural infection and it is suggested that very high antigen levels are needed for vaccine-induced CD4+ effector T-cells to become memory T-cells." (PMID 36052083, 2022). "First, CD4 T cell dynamics in adults are typically described as a balance between a constant total rate of influx and a constant per capita rate of loss, leading to steady trajectories in the absence of infection." (PMID 35969641, 2022).
infection (continued). "Furthermore, epidermal CD11c+ DCs expressed significantly higher levels of surface CCR5 than LCs and correspondingly supported higher levels of infection making them also more efficient than LCs at second phase (in cis) transfer of the virus to CD4 T cells at 72–96 h." (PMID 35173293, 2022). "To evaluate whether the unequal proportion of full-length proviruses across the CD4+ T cell subsets can be observed at early stages of infection, we sorted memory Tcm, Ttm, and Tem CD4+ T cells from 3 HIV-1– donors and infected them for 20 hours with the HIV-1 laboratory strain, NL4-3." (PMID 35133986, 2022). "Thus, while naturally occurring CD4+ CD4-MBL CAR-T cells could be infected and eliminated, the CD8+ CD4-MBL CAR-T cells are protected from infection." (PMID 36582226, 2022). "Meanwhile, it has been demonstrated in the JEV-infected mouse models that JEV infection-induced myeloid-derived suppressor cells (MDSCs) could suppress CD4+ T-cell immune responses then lead to decreased B-cell populations and humoral immunity and finally facilitate the progression of infection." (PMID 35463639, 2022). "Additionally, during acute infection, B-cells could affect cytokine responses of CD4+ T-cells generating fewer effector memory cells and higher expression of Bcl-6." (PMID 36148227, 2022). "Therefore, it is likely to underestimate the proportion of SARS-COV-2 expanded TCR sequences associated with incident infection in our participants because it will not include either private or CD4+ TCR specificities." (PMID 35474751, 2022). "The latent reservoir is established immediately following infection, as early as 3 dpi, and prior to detectable viremia, in resting CD4+ T cells: with different immunophenotypes: central memory, transitional memory, stem cell memory T cells, Tregs, and follicular T helper CD4+ cells." (PMID 35062339, 2022). "To ascertain if differences in receptor-ligand interactions could be responsible for the impaired capacity of the NK cells to kill the TCD32dim subset, we studied the expression of MICA/B, ULBP-1, CD155, and HLA-E on the surface of HIV-infected CD4+ T cells after ex vivo infection." (PMID 35616530, 2022). "Thus, the convalescents still maintain SARS-CoV-2 specific effector memory T cells, particularly CD4+ T cells that could trigger T cell reactivation during a SARS-CoV-2 re-infection at 1-year after initial infection." (PMID 35240947, 2022). "Similarly, it is currently unknown whether DCs in later stages of infection remain vital for coordinating CD4+ T cell function and cytokine secretion, or if other antigen presenting cells (APCs) adopt more dominant roles in this context." (PMID 35958580, 2022). "Uninfected CD4+ T cells and monocytes may also enter the CNS contributing to amplified infection." (PMID 35775044, 2022). "The results show that degree of internalization of plasma EVs from mice at different infection stages were similar in the same immune cells, namely, CD4+ and CD8+ T cells, B cells and MDSC, which may be related to the origin of EVs and the mechanism of internalization." (PMID 35360110, 2022). "Notably, the top five clones for each mouse (which ranged from comprising 3.7 to 9.8% of the GP66-specific pool) accounted for ~40–45% of all cells in the dataset, demonstrating that the CD4+ T cell response during LCMV Cl13 infection is dominated by a few large clones." (PMID 36255051, 2022). "As TB is a disease primarily controlled by CD4+ T-cell responses, as a first application, we investigated these optimized LVs for their potential in inducing T-cell responses against selected Mtb antigens with preferential expression at distinct infection phases." (PMID 36104497, 2022).
infection (continued). "However, our knowledge of the phenotypic and functional diversity of CD8+ cytotoxic lymphocytes, CD4+ T helper cells, mucosal-associated invariant T (MAIT) cells and CD4+ T follicular helper (Tfh), which play a critical role in infection control as well as long-term protection, is still evolving." (PMID 35833134, 2022). "As most of the anti-spike T-cell response following natural infection is from CD4+ T cells, this observation could also be explained by boosting of pre-existing responses below the threshold of detection, which are mostly CD4+ T cells." (PMID 34778853, 2022). "To determine the type of cellular response induced upon infection in the immunized mice and controls, we evaluated the expression of the transcription factors T-bet, GATA-3 and RORγt, respectively, associated with Th1, Th2 and Th17 cell populations in antigen-experienced (CD44+) CD4+ T cells." (PMID 35746533, 2022). "Furthermore, increased CD4+IL-10+ was observed in the lungs in comparison to the Infection group." (PMID 36119106, 2022). "Furthermore, the need for HIF-1α expression to mediate both IFN-γ-mediated and IFN-γ-independent CD4 T cell control emphasizes the central role of HIF-1α in cell-intrinsic control of infection and indicates that these two pathways of macrophage activation converge on HIF-1α activation." (PMID 35877763, 2022). "Some of these properties might be explained by preferential infection of Tregs over other CD4 + T cell subsets, which is shown in our model and others, and suggests that the epigenetic programming of T cells destined for resting and suppressive fates might impact latency outcomes." (PMID 35804422, 2022). "We show that expression of Id3 definitively identified a subset of cells within both the CD4+ Tfh and T helper 1 (Th1) lineages at memory time points that exhibited memory potential, with the capacity for significant re-expansion in response to secondary infection." (PMID 35858332, 2022). "Interestingly, we observed that frequencies of IAV- and SARS-CoV-2-specific IFN-γ positive CD4+ T cells were remarkably lower in coinfection groups than in single infection group, although the IAV- and SAR-CoV-2-specific IFN-γ positive CD8+ T cells were similar among both." (PMID 35107382, 2022). "However, other cell types, such as epithelial and endothelial cells, can also upregulate MHC class II expression upon infection or in response to other sources of inflammatory stimuli and may be targets for CD4 T cell killing." (PMID 36445084, 2022). "The non-specific and uncontrolled activation of CD4+ T cells maybe the cause and effect of heightened inflammation observed in WT infection." (PMID 34716845, 2022). "Overall, these data show that, upon infection, the development of cerebral trypanosomiasis is associated with the recruitment of inflammatory monocytes to the brain vasculature, most of which express ICAM1, and the infiltration of CD4+ T cells into the brain parenchyma." (PMID 35787830, 2022). "In contrast, IgD+IgMlow classical MBCs and two populations of atypical MBCs (IgM+IgD+ and class‐switched T‐bet+ cells) expressing low or no CXCR5 and CCR6, along with CD127+CD25low TH2‐like memory CD4+ T cells, were associated with reduced odds of symptomatic infection." (PMID 35475529, 2022). "No obvious change or reduction in Tfr (CXCR5+PD1+CD4+FOXP3+) cells.Tfr cells may limit the immune effect caused by a persistent antigen or infection." (PMID 36389806, 2022). "However, while IFN-γ production by CD4 T cells is most likely necessary for full control of infection, it has become clear that IFN-γ is a poor biomarker for effective CD4 T cell immunity to TB and that CD4 T cells are capable of controlling infection even in the absence of IFN-γ." (PMID 35877763, 2022).
infection (continued). "Although humoral and CD4+ T-cell immunity is essential to prevent early infection of viral pathogens, CD8+ T-cells might be necessary for controlling replication once the infection has been established and they are essential in reducing the severity of the disease." (PMID 35746733, 2022). "Previous studies suggested that LIS1-deficient CD4+ and CD8+ T cells fail to proliferate in response to cytokine-driven homeostatic signals but successfully divide in response to TCR cross-linking in vitro or following infection with a Listeria monocytogenes strain expressing ovalbumin." (PMID 36519536, 2022). "Depending on the trypanosome species and the stage of infection, different cellular sources could contribute to IL-10 production such as NK cells, CD8+ T cells and CD4+ T cells around peak parasitaemia as well as B cells and plasma cells, myeloid cells and hepatocytes as the infection progresses." (PMID 35464430, 2022). "Considering that our patients had severe impairment of cell-mediated immunity (median CD4+ T cell counts of 99 × 106/L) and the median viral load (2.52 × 105 copies/ml) was similar to or higher than that reported in previous studies indicated a greater likelihood of infection." (PMID 35992169, 2022). "Favoring this hypothesis, we showed that adoptive transfer of CD4+GzB+ T cells to susceptible Il18ra-/- mice, which have lower levels of these cells, significantly increased their survival to infection without, however, affecting parasite loads." (PMID 35670567, 2022). "As expected, HIV-C only caused low-level productive infection of CD4+ T cells regardless of whether they were preincubated or not with AraC due to the low-level expression of complement receptors." (PMID 35204813, 2022). "Therefore, we speculated that uroepithelial cells may secrete AMPs not only during infection, but also in response to CD4-PP." (PMID 35821354, 2022). "Moreover, HTLV-1 and HTLV-2 can be detected equivalently in both T-cell subsets during initial infection in vivo, and during in vitro immortalization, CD4+ and CD8+ T-cells proliferate comparably, until one population is selected for predominant clonal expansion." (PMID 35062342, 2022). "In addition, quantification of virus release by performing SG-PERT assays for reverse transcriptase activity in culture supernatants showed that infection of both Jurkat and primary CD4+ T cells with W757A virus resulted in a significant reduction in HIV-1 budding compared to WT virus." (PMID 35062333, 2022). "Finally, our results suggest that calcitriol can decrease the protein expression of SIGLEC-1 and DC-SIGN, receptors widely related to trans-infection, suggesting that this is at least one of the possible mechanisms by which calcitriol reduces viral transfer to CD4+ T cells." (PMID 35802715, 2022). "Recurrent infection is likely to be influenced by a number of factors but the depletion of CD4+CD8+ thymocytes during thymic atrophy, detected in this study in infected mice, may also play a role in recovery from infection or susceptibility to recurrent disease." (PMID 36045589, 2022). "Individual spike‐specific CD4+ T‐cell responses seemed to be long‐lasting since we could still detect dominant responses 196 days (individual HH‐SP‐35) after the last vaccination and 448 days (individual HH‐SP‐08) after resolved infection." (PMID 35957961, 2022). "Therefore, we hypothesize that higher levels of PRRSV-specific CD4 CTL are crucial for sows to clear heterologous infection and to protect from transplacental infection." (PMID 36798517, 2022). "In CHIKV infection, the CD4+ T cells migrate to synovium, leading higher concentrations of IFN-γ, but these cells mediated joint inflammation independently of IFN-γ, suggesting that IFN-γ is not the single factor associated with joint pathology during infection." (PMID 35456119, 2022).
infection (continued). "In addition to neutralizing antibodies, 2019-nCoV can also induce a cellular immune response, and the levels of 2019-nCoV-specific CD4+ and CD8+ T cells are associated with mild symptoms after infection, suggesting the protective role of T cell immunity in 2019-nCoV infection." (PMID 35891313, 2022). "Infection may affect memory-activated CD4+ T cell infiltration and lymph node invasion." (PMID 34938284, 2021). "However, it has been shown that following infection of laboratory mice with C. albicans, while the initial IL-17-producing cells were γδ T cells, at later times the majority of C. albicans-reactive IL-17-producing T cells were CD4+ Tsrm cells." (PMID 33796109, 2021). "Similarly, except for the 6th week after infection, CD4+TIGIT+ T cells also had the same changes, indicating that T. gondii infection stimulated the host TIGIT+ TEM cells to proliferate, migrate to the inflammatory surrounding tissue, and produce cytokines to control T. gondii infection." (PMID 34421855, 2021). "CD4-deficient mice treated with an anti-CD4 antibody could not clear the infection, as well as CD4+ T cells deficiency is related to chronic giardiasis." (PMID 34778111, 2021). "The ability of lncRNAs to regulate CD4+T cell differentiation could have crucial implications for CE, with a Th1-predominant immune response in the early infection stage and a Th2-predominant immune response in the late infection stage." (PMID 34082780, 2021). "Therefore, we could demonstrate trans-infection of CD4+ T lymphocyte subsets solely mediated by vaginal epithelial cells in the absence of accessory cells such as monocytes and dendritic cells otherwise present in a stimulated PBMC population." (PMID 33816339, 2021). "Upon examination of sequestered T cells during infection, the PbYOP1-deficient parasites had attenuated virulence without influencing sequestration of the total CD4+ and CD8+ T cells in the brain, and the frequency and cell number were comparable between WT and 106Pbyop1Δ-infected mice." (PMID 34025654, 2021). "However, in contrast to ADE, infection of CD4+ cells remains dependent on the presence of ACE2." (PMID 34239884, 2021). "In addition to HIV receptors, cofactors on CD4 T cells, such as CD26, α4β7 integrin, and lymphocyte-function-associated antigen (LFA-1) may play roles in facilitating infection." (PMID 34960781, 2021). "However, the positive correlation of CD4+ EM T cells with Campylobacter hyointestinalis may indicate recurrent infection and the expansion of a pathogen-specific T cell subset." (PMID 34158595, 2021). "Thus, despite multiple potential cellular sources of IL-10, GC B cell, GC-TFH cell and parasite-specific antibody impairments observed in Plasmodium-infected mice treated with α-IL-10R antibody were phenocopied by infection of mice harboring Il10-/- CD4 T cells." (PMID 33529242, 2021). "Moreover, subjects with more severe disease demonstrate an increased breadth and magnitude of the memory CD4 T cell response, which could lead to the larger and broader antibody response of subjects with more severe infection, as observed in our study." (PMID 33468695, 2021). "Interestingly, many clusters of memory cells were also not preferentially targeted, consistent with the notion that not all memory CD4+ T cells are equally susceptible to infection." (PMID 33910003, 2021). "Productively infected (double-positive, DP) and latently infected (single mCherry-positive, mC) CD4+ T cells were clearly distinguishable, and the percentage of the DP cells was roughly 16 times more than the single mC-positive cells on day 3 post-infection (p.i.)in STCM (Super T cell medium)." (PMID 33835029, 2021). "In addition, an in vivo study in mice with a cDC having a conditional deletion in the gene for Atg5 showed impaired CD4+ T cell priming after infections with HSV-1 or HSV-2, with the most pronounced defect from Atg5 deletion being the processing and presentation of phagocytosed antigens in MHC-II." (PMID 34895058, 2021).